KDM5D (lysine demethylase 5D)
Diseases named in the same sentence as KDM5D in open-access papers (continued):
Sharing a sentence is not in itself a finding about the gene and the disease.
cancer (continued). "One notable case that should be mentioned, is that of KDM5D which has been very heavily studied with respect to cancer metastasis and its suppressive effects in numerous contexts and continues to be a locus of extreme interest in contemporary cancer research." (PMID 41214505, 2025). "In addition, KDM5D can reduce malignant gene expression and inhibit the development of various cancers." (PMID 40145017, 2025). "Of all the ChrY loci discussed, KDM5D has the greatest relevance to the prevention and suppression of metastasis because it has been repeatedly identified in various male predominant/exclusive cancers." (PMID 41214505, 2025). "KDM5D drives sex differences in male osteogenesis, cardiomyocyte, and cancer." (PMID 39567827, 2024). "Considering the inhibitory role of KDM5D in various cancers, exploring the mechanism of KDM5D in male BC may become an academically valuable and attractive topic." (PMID 38769556, 2024). "In addition, an Oncomine cancer database analysis revealed significantly lower KDM5D expression in CRPC patient samples with a poorer cancer prognosis and treatment outcome." (PMID 35884386, 2022). "Interestingly, KDM5D deletion from cancer cells may decrease cancer invasiveness and enhance CD8+ T cell-killing activity; hence, it can be a promising therapeutic approach for CRC male patients expressing mutant KRAS33." (PMID 39327445, 2024). "Thus, identifying a common regulator (such as KDM5D) of cancer stemness, a diapause-like state, and treatment resistance may help in the development of a strategy for targeting drug-tolerant persister HNSCC cells." (PMID 36982384, 2023). "Thus, KDM5D is closely related to the epigenetic regulation of cell cycle control in cancer." (PMID 36982384, 2023). "Overall, the data highlight KDM5D/AURKB axis in which KDM5D modulates AURKB expression generates platinum-tolerant persister cells, enhances cancer stemness potential, activates the diapause-like state, and alters platinum sensitivity in HNSCC." (PMID 36982384, 2023). "By modulating mRNA levels of AURKB, KDM5D promoted the generation of platinum-tolerant persister cells in vitro, leading to the identification of the KDM5D/AURKB axis, which regulates cancer stemness and drug tolerance of HNSCC." (PMID 36982384, 2023). "A specific histone demethylase, namely lysine-specific demethylase 5D (KDM5D), is overexpressed in diverse types of cancers and involved in cancer cell cycle regulation." (PMID 36982384, 2023). "In myeloid malignancies KDM5A and KDM5B show enzymatic activity towards H3K4me3 while little is known about KDM5C and KDM5D in this context." (PMID 34944554, 2021). "Moreover, several confirmed gender-related carcinogenic genes exhibit completely different distributions in male and female cancer samples, such as PIK3CA, NF1, EIF1AY, IGF1R, NRAS, KDM5D, UTY, and PPP6C." (PMID 39541191, 2024). "Our data also demonstrated a negative feedback loop between KDM5D and p38, where they mutually limit each other’s activity or expression, implying a more complex regulatory circuitry, perhaps to impose homeostatic expression of these genes in cancer cells." (PMID 41308413, 2025). "Thus, the interplay of KDM5D and KDM1A may have resulted in the clinicopathological findings of the present study, because the final effect on chromatin structure and genome function in most cancers is not strictly dependent on one histone modification." (PMID 37974379, 2024).
neurodegenerative disease (1 paper, 2024). A disorder of the central nervous system characterized by gradual and progressive loss of neural tissue and neurologic function. "Although HMGN4, KDM5D, and RBBP4 have not been directly correlated with PD, the dysregulation of chromatin-modifying complexes has been implicated in various neurodegenerative diseases, including PD." (PMID 38279299, 2024).
KDM5D also shares sentences with these, for which no sentence is quoted: cardiomyopathy (2 papers); clear cell renal cell carcinoma (2); liver cancer (2); adenocarcinoma (1); adenoma (1); amyotrophic lateral sclerosis (1); autism (1); benign prostatic hyperplasia (1); bone metastasis (1); breast tumor (1); chronic GVHD (1); Cirrhosis (1); colitis (1); colorectal adenocarcinoma (1); glioblastoma (1); graft versus host disease (1); heart failure (1); hematological malignancies (1); hepatocellular adenoma (1); Huntington disease (1); idiopathic dilated cardiomyopathy (1); infection (1); Insulin resistance (1); laryngeal squamous cell carcinoma (1); melanoma (1); Obesity (1); pancreatic adenocarcinoma (1); pancreatic cancer (1); renal cell carcinoma (1); spermatogenic failure (1).
A further 2 diseases each share a sentence with KDM5D in 1 paper.